TGFB1 (transforming growth factor beta 1)
Diseases named in the same sentence as TGFB1 in open-access papers (continued):
Sharing a sentence is not in itself a finding about the gene and the disease.
ovarian carcinoma (continued). "We also examined the protein expression of TGFβ (gene TGFB1), a protein that induces TGFBI and is implicated in EMT in ovarian cancer." (PMID 36463238, 2022). "For example, a study reported that TAFs-derived exosomes can activate the TGFβ1 signaling to promote epithelial-mesenchymal transition of ovarian cancer cells." (PMID 35587143, 2022). "This study is the first evidence to show that Wnt5A is required for TGFβ1-induced EMT in ovarian cancer." (PMID 35053353, 2022). "Transwell invasion, adherence and 3D tumor spheroid invasion assays were employed to test the effects of TGFβ1 on the invasion and adhesion of ovarian cancer spheroids." (PMID 34621667, 2021). "SMYD3 and ITGB6 activated the TGFβ1/Smad3 pathway and then induced the upregulation of Snail, Vimentin and N-cadherin and the downregulation of E-cadherin in 3D-cultured ovarian cancer spheroids." (PMID 34621667, 2021). "For example, previous research proved that TGFβ1 in fibroblasts-derived exosomes promoted epithelial mesenchymal transition of ovarian cancer cells." (PMID 33627162, 2021). "SB431542 has also been tested as a treatment for NSCLC or ovarian cancer, showing its capability to avoid the effects of TGFβ1 and revert EMT." (PMID 33498521, 2021). "Here, we observed that in ovarian cancer spheroids, the Smad3 pathway was activated by TGFβ1 and upregulated the expression of Snail and N-cadherin, which are crucial genes in the EMT process." (PMID 34621667, 2021). "Meanwhile, MARCH5 expression was significantly higher in epithelial ovarian cancer than in normal ovary tissues, whereas silencing MARCH5 decreased TGFβ1-induced ovarian carcinomas autophagy, migration, and invasion in vitro and in vivo." (PMID 34680446, 2021). "TGFβ1 is significantly up-regulated in exosomes from CAFs in ovarian cancers with omental metastasis; TGFβ1 promotes EMT in ovarian cancer through activation of SMAD2/3 signaling." (PMID 32957712, 2020). "Further, CAF-derived exosomes contain TGFβ1; exosomal TGFβ1 enhanced the migration and invasion ability of ovarian cancer cells and the promotion of epithelial-mesenchymal transition (EMT) by activating the SMAD signaling." (PMID 32230983, 2020). "TGFβ1 treatment decreased the surface expression of MHC-I of hypomethylated ovarian cancer cells, while TGFβ inhibition restored its normal expression level." (PMID 33149148, 2020). "When ovarian cancer cells ingest TGFβ1-enriched CAF-exosomes, they upregulate TGFβ1 expression and become more adept at migration and invasion via a SMAD signaling cascade." (PMID 31409361, 2019). "TGFβ1 from the metastasizing ovarian cancer cells can induce the mesothelial cells to secrete plasminogen activator inhibitor type 1 (PAI-1), which leads to an increased invasion of cancer cells through the mesothelial cell layer." (PMID 31640297, 2019). "Inhibitor of DNA binding 1 (Id-1), a protein repressed by miR-29b, facilitates the TGFβ1-induced EMT in human ovarian cancer cells." (PMID 30250403, 2018). "Collectively, these findings indicated that miR-490-3p was essential for TGFβ1-induced EMT of ovarian cancer cells regulated by CCAT1 depletion." (PMID 30250403, 2018). "Our findings shed lights on how CCAT1 regulates TGFβ1-promoted cancer metastasis and facilitate development of effective therapies for treating ovarian cancer." (PMID 30250403, 2018). "In this study, our results demonstrated that lncRNA CCAT1 enhanced TGFβ1-induced metastatic process of ovarian cancer cells via miR-490-3p/TGFβR1 axis, which was crucial for developing targeted drugs for treating ovarian cancer patients with advanced stage." (PMID 30250403, 2018). "Here, our results demonstrated that lncRNA CCAT1 enhanced TGFβ1-induced metastatic process of ovarian cancer cells via miR-490-3p/TGFβR1 axis in ovarian cancer cells." (PMID 30250403, 2018).
ovarian carcinoma (continued). "Transwell matrix penetration assay demonstrated that knockdown of CCAT1 reduced the number of invasive ovarian cancer cells (by ~ 50%) in the presence of TGFβ1 compared to sh-NC group." (PMID 30250403, 2018). "Wound healing and invasion assay were employed to investigate the role of CCAT1 and miR-490-3p in the TGFβ1-induced migration and cell invasion of ovarian cancer cells, respectively." (PMID 30250403, 2018). "In this study, we highlight that knockdown CCAT1 represses TGFβ1-induced EMT of ovarian cancer cells through miR-490-3p/TGFβR1 axis." (PMID 30250403, 2018). "TGFβ1 was reported to upregulate TG2 in ovarian cancer by upregulating the activity of NFκB and via the ERK and PI3/AKT pathway in diseased pulmonary fibroblast." (PMID 28223538, 2017). "The elevated expression of TGFβ1 in the CAF exosomes induced ovarian cancer cell EMT, which was accompanied by a notable decrease in E-cadherin and an increase in vimentin expression." (PMID 29221185, 2017). "We showed that TGFβ1 in fibroblast exosomes contributes to EMT in ovarian cancer cells, including the migration and invasion in ovarian epithelial cells, suggesting that CAF-derived exosomes promote ovarian cancer progression and metastasis." (PMID 29221185, 2017). "We also examined the phosphorylation levels of SMAD2/3 in ovarian cancer cells after exogenic TGFβ1 stimulation." (PMID 29221185, 2017). "In conclusion, our results demonstrated that CFG suppresses ovarian cancer cell proliferation as well as TGFβ1-induced EMT in vitro." (PMID 28036353, 2016). "In previous studies, a proportion of prostate, bladder, gastric, hepatocellular, and ovarian cancers showed sensitivity to TGFβ1 and their growth was inhibited by stimulation with TGFβ1." (PMID 25826092, 2015). "In ovarian cancer cell line expressions of transforming growth factor beta 1 (TGFB1) and TNC are significantly related." (PMID 26313571, 2015). "TGFB1 is a well-characterized inducer of EMT in ovarian cancer and human squamous cell carcinoma cells, resulting in increased cell migration and invasion." (PMID 23865481, 2013). "Furthermore, its expression correlated with the mRNA levels of several stem-cell and EMT-related genes including LIN28, OCT4, VIM, and TGFB1 in the L1CAM+/CD133+ cell populations derived from ovarian cancer IGROV1 and SKOV3ip cells." (PMID 40429728, 2025). "Furthermore, TGFB1 was proposed to contribute to immunosuppression and disease progression in ovarian cancer via the induction of TGFBI in macrophages." (PMID 37370765, 2023). "Macrophage-produced TGFB1 supports an immunosuppressive microenvironment in ovarian cancer." (PMID 38031074, 2023). "In order to place our results within the context of clinical ovarian cancer, we analyzed existing TCGA datasets and asked whether expression of TGFB1 and BRCA2 were related." (PMID 37568736, 2023). "Activated platelets secrete TGFβ1, increasing the proliferation of ovarian cancer cells." (PMID 35626102, 2022). "We also show that the EMT phenomenon in T2-KD and gRNA2 ovarian cancer cells may be mediated by a significant upregulation of TGFβ1 expression." (PMID 36585738, 2022). "Since the TGFβ1/Smad3 signal transduction pathway is involved in inducing EMT in ovarian cancer, we aimed to identify whether the TGFβ1/Smad3 pathway is more activated in 3D-cultured ovarian cancer spheroids than in 2D-cultured ovarian cancer cells." (PMID 34621667, 2021). "In this report, we found that SMYD3 and ITGB6 could promote the release and activation of latent TGFβ1 and increase the phosphorylation of Smad3 activated by TGFβ1 in ovarian cancer spheroids." (PMID 34621667, 2021). "ELISA was performed to assess the release of latent TGFβ1 from ovarian cancer spheroids." (PMID 34621667, 2021). "Higher phosphorylation levels of Smad3 were found in 3D-cultured HEY and A2780 cells than in 2D-cultured cells, which indicated that TGFβ1/Smad3 might play a role in promoting the EMT process in ovarian cancer spheroids." (PMID 34621667, 2021).
ovarian carcinoma (continued). "Nevertheless, more studies on the role of TGFβ1 in ovarian cancer metastasis are required." (PMID 34621667, 2021). "Using breast, pancreatic, and ovarian cancer cells, transforming growth factor beta-1 (TGFB1) or epidermal growth factor (EGF) treatment or SNAI1 overexpression increased stemness and reduced let-7 expression, while SNAI1 knockdown reduced stemness and increased let-7 expression." (PMID 33806868, 2021). "It is necessary to investigate whether ITGAV could regulate the activation of latent TGFβ1 in 3D-cultured ovarian cancer spheroids and whether ITGAV is involved in the ITGB6-regulated activation of latent TGFβ1 in 3D-cultured ovarian cancer spheroids." (PMID 34621667, 2021). "Similarly, TGFB1 provokes the demethylation of vtRNA2-1 promoter and consequently increases its expression in ovarian cancer (Ahnet al., 2018)." (PMID 34354812, 2021). "When ovarian cancer spheroids were treated with latent TGFβ1, the activation of the Smad3 pathway could also be inhibited if ITGB6 was blocked by a specific antibody." (PMID 34621667, 2021). "TGFβ1 from ovarian cancer cells can also induce MMT by increasing RhoA activity." (PMID 31640297, 2019). "All these revealed that TGFβ1 induced EMT of ovarian cancer partly dependent on lncRNACCAT1." (PMID 30250403, 2018). "However, little is known about the detailed mechanism of how TGFβ1 induces EMT of ovarian cancer cells." (PMID 30250403, 2018). "However, little is known about the detailed mechanism of how CCAT1 enhances TGFβ1-induced EMT of ovarian cancer cells." (PMID 30250403, 2018). "Several studies suggest that the TGFβ1 is involved in ovarian cancer EMT progression." (PMID 30250403, 2018). "The results showed that scramble (sh-NC) cells exhibited no migration difference compared to control, whereas CCAT1 knockdown (sh-CCAT1) cell significantly compromised migration (reduced by ~ 40–50%) of ovarian cancer cells induced by TGFβ1 in relative to sh-NC group." (PMID 30250403, 2018). "However, the TGFβ1 neutralizing antibody reduced the migration and invasive capacity of the ovarian cancer cells to levels that were similar to the control." (PMID 29221185, 2017). "Thus, our data showed that the TGFβ1 in CAF-derived exosomes supports the ovarian cancer cell towards a pre-metastasis state." (PMID 29221185, 2017). "Furthermore, ubiquitin specific protease 22 (USP22), high levels of which are associated with EOC and poor prognosis, have been shown to regulate the cell cycle pathway downstream of TGFβ1, consequently stimulating ovarian cancer cell proliferation." (PMID 28758950, 2017). "Our results indicate that the role of TGFβ1 in CAF exosomes triggers ovarian cancer cells into a more aggressive phenotype, suggesting that targeting CAF exosomes could be a potential treatment in ovarian cancer." (PMID 29221185, 2017). "We found that anti-ITGB6 antibody was more effective in inhibiting the phosphorylation level of Smad3 in 3D-cultured NC-ITGAV cells than in 3D-cultured si-ITGAV cells, implying that ITGAV might play a role in ITGB6-regulated activation of latent TGFβ1 in 3D-cultured ovarian cancer spheroids." (PMID 34621667, 2021). "Moreover, SMYD3 and ITGB6 could facilitate the release of latent TGFβ1 from 3D-cultured ovarian cancer spheroids." (PMID 34621667, 2021). "Hence, SMYD3 and ITGB6 could not only activate latent TGFβ1 but also increase the release of latent TGFβ1 from 3D-cultured ovarian cancer spheroids." (PMID 34621667, 2021). "However, ITGAV might be play a role in the ITGB6-regulated activation of latent TGFβ1 in 3D-cultured ovarian cancer spheroids." (PMID 34621667, 2021). "Our results demonstrated that the SMYD3/ITGB6/TGFβ1-Smad3 positive feedback loop could promote the invasion and adhesion of ovarian cancer spheroids by upregulating the expression of N-cadherin, Snail, and Vimentin and downregulating the expression of E-cadherin." (PMID 34621667, 2021).
ovarian carcinoma (continued). "Therefore, SMYD3 and ITGB6 could stimulate the TGFβ1/Smad3 pathway and regulate the expression of N-cadherin, Snail, Vimentin, E-cadherin in ovarian cancer spheroids and promote the EMT process." (PMID 34621667, 2021). "To test this hypothesis, we treated two MHC-Ihigh-expressing ovarian cancer cell lines with TGFβ1." (PMID 33149148, 2020). "In addition, TGFβ1 did not significantly inhibit the cell proliferation in 18 (78%) of 23 ovarian cancer primary cultures, indicating that TGFβ1 signaling might be impaired in ovarian cancer cells." (PMID 30791431, 2019). "Following the bioinformatics analysis, the study explored the expression levels of CCL2, IL10, IL6, and TGFβ1 in normal ovarian epithelial cells (HOSE) and ovarian cancer cells (SKOV3)." (PMID 39981173, 2025). "Several of the analyzed genes (TGFβ-1, IL19, CXCR4, BMP1, VCAN, and WNT2) showed elevated expression across multiple cancer types in pan-cancer datasets, including lung, colon, and ovarian cancers." (PMID 41348904, 2025). "Peritoneal fluid in ovarian cancer contains increased concentrations of HGF (hepatocyte growth factor), TGF-β1 (transforming growth factor beta-1), and GRO-1 (growth-related oncogene-1)." (PMID 38791014, 2024). "Our study reveals that all the known typical and tested atypical DUSPs are expressed at various levels in the ovarian cancer cell line SKOV3 and TGFβ1 treatment leads to marked changes in the expression of several DUSPs." (PMID 37476896, 2023). "TGFB1 is positively regulated by a feedback loop involving FXYD5, TGF β/SMADs signaling drives EMT during ovarian cancer progression." (PMID 38031074, 2023). "DAB2 expression had significant positive correlations with mesenchymal markers (ZEB2, TGFβ1, SNAI2, ZEB1, FN1, MMP2, TWIST1 and MMP3) and CSC markers (CD44 and MYD88) in ovarian cancer cell lines (CCLE) and tissues (TCGA: RNA sequencing and microarray)." (PMID 37815603, 2023). "To test if PVT1 changes in response to cell density were a feature of mesenchymal cells, we induced EMT in epithelial ovarian cancer OVCAR3 and OVCA420 cells with TGFβ-1." (PMID 35820706, 2022). "Direct and indirect co-cultures showed that epithelial ovarian cancer cells induced ADSCs to express CAF markers, including α-SMA and fibroblast activation protein, via the transforming growth factor beta 1 (TGF-β1) signaling pathway." (PMID 33498240, 2021). "When ovarian cancer cells take up TGFβ1-enriched CAF exosomes, they upregulate TGFβ1 expression, activating migration and invasion through an SMAD signaling cascade." (PMID 33228245, 2020). "To characterize the role of CCAT1 in TGFβ1-induced EMT of ovarian cancer cells, we first determined the expression level of CCAT1 in SKOV3 and CaOV3 cells when treated with 10 ng/ml TGFβ1 for 48 h." (PMID 30250403, 2018). "Next, we observed that miR-490-3p overexpression greatly attenuated migration of ovarian cancer cells SKOV3 and CaOV3, whereas exogenous expression of miR-490-3p and TGFβR1 rescued TGFβ1-induced migration change of the cells." (PMID 30250403, 2018). "This new molecular axis was confirmed to be important for TGFβ1-induced EMT of ovarian cancer; however, other possible mechanisms responsible for CCAT1-mediated metastasis of ovarian cancer cells remains to be investigated for the future." (PMID 30250403, 2018). "And then we employed wound healing method to examine the migration of CCAT1-depleted ovarian cancer cells SKOV3 and CaOV3 in the presence of TGFβ1(10 ng/ml)." (PMID 30250403, 2018). "Studies have demonstrated that transforming growth factor beta-1 (TGF-β1) exhibits oncogenic activity in different types of cancer, including ovarian cancer (OC)." (PMID 30594239, 2018). "In this study, we first proved that TGFβ1 upregulated expression of lncRNACCAT1 in ovarian cancer cells and knockdown of CCAT1 inhibited TGFβ1-induced EMT." (PMID 30250403, 2018).
ovarian carcinoma (continued). "Previous studies showed that TGFβ1 and TGFβ2 were both capable of inducing complete EMT in OVCA429, a clear-cell ovarian cancer cell line, but a partial EMT was observed in OVCAR3, a serous ovarian cell." (PMID 29221185, 2017). "Our results showed that CAF express significantly higher TGFβ1 levels than normal fibroblasts, and the transfer of exosomes from CAF to neighboring cancer cells promotes EMT in ovarian cancer, which thus initiates tumor progression and metastasis." (PMID 29221185, 2017). "Ovarian cancer cells secrete TGFβ1 to activate a TGFβ1/RAC1/SMAD-mediated signaling pathway in mesothelial cells that results in secretion of fibronectin by mesothelial cells and increased ovarian cancer cell adhesion, invasion, and proliferation." (PMID 28275576, 2017). "Studies have reported the presence of some common genetic variations in the TGF-β signaling pathway to be related to ovarian carcinogenesis, such as TGFB1: rs56361919 in 23% of ovarian cancer cases." (PMID 21984931, 2011). "3D spherical models of ovarian cancer have been used to shed light on the impact of both integrin beta-6 (ITGB6) and SET and MYN-domain containing 3 (SMYD3) on the activation of the TGFβ1/Smad3 pathway and downstream upregulation of N-cadherin and downregulation of E-cadherin." (PMID 38254117, 2024). "Although a limited number of DUSP expressions have been studied in ovarian cancer, regulation of DUSP expression by TGFβ1 in serous ovarian carcinoma cells is currently unknown." (PMID 37476896, 2023). "Furthermore, TGFB1 enhances autophagy and mitophagy through PI3K/Akt and Ras-Raf-MEK-ERK pathways in ovarian cancer." (PMID 38031074, 2023). "For the following genes, we found no significant changes in expression in fibroblasts after treatment with exosomes from ovarian cancer cells: HTATIP2 (HIV-1 Tat interactive protein 2, 30 kDa), IL1B, TGFB1 and TNFSF10 (TRAIL, Tumor necrosis factor (ligand) superfamily, member 10)." (PMID 36012171, 2022). "Interestingly, attenuating the expression of SMYD3 and ITGB6 also decreased the release of latent TGFβ1 from ovarian cancer spheroids, which further demonstrated the regulatory roles of SMYD3 and ITGB6 in TGFβ1 pathway activation." (PMID 34621667, 2021). "According to reports and our research base, we speculated that SMYD3/ITGB6 promotes the invasion and adhesion of ovarian cancer spheroids by changing the configuration of TGFβ1-LAP and then activating TGFβ1." (PMID 34621667, 2021). "Thus, the SMYD3/ITGB6/TGFβ1 positive feedback loop drove the upregulation of Snail and N-cadherin, which promoted invasion, adhesion and EMT progression during ovarian cancer metastasis." (PMID 34621667, 2021). "TGFβ1 and 2 have demonstrated roles in ovarian cancers, however, it is not clear if TGFβ3 plays a direct role in EOC despite a few lines of evidence indicating potential roles in ovarian angiogenesis." (PMID 33590419, 2021). "For patients with advanced-stage ovarian cancer, a bi-shRNAfurin/GMCSF-expressing autologous tumor cell (FANG) vaccine capable of decreasing TGFβ1/2 protein expression, was demonstrated to improve immune response and recurrence free survival in a phase II trial." (PMID 31888563, 2019). "In two ovarian carcinoma cell types (OVCCRI and IGROVI) a different effect of TGFβ has been observed, in which TGFβ1 could induce cell cycle arrest at the G1/S transition in OVCCRI but not in IGROVI cells." (PMID 28758950, 2017). "Although the role of TGFβ in ovarian cancer has been studied extensively, the function of TGFβ1 and TGFβ2 in exosomes remains to be explored to understand how these cytokines contribute to EMT in ovarian cancer." (PMID 29221185, 2017). "In OV-Mz-6 ovarian cancer cells, expression of KLK4–7 leads to elevated TGFβ-1 signaling." (PMID 29249975, 2017).